PLPPR4 (phospholipid phosphatase related 4)
Description:
Postsynaptic density membrane protein that indirectly regulates glutamatergic synaptic transmission through lysophosphatidic acid (LPA)-mediated signaling pathways. Binds lysophosphatidic acid (LPA) and mediates its internalization into cells. Could act as receptor or a transporter of this lipid at the post-synaptic membrane (By similarity). Modulates lysophosphatidic acid (LPA) activity in neuron axonal outgrowth during development by attenuating phospholipid-induced axon collapse (By similarity).
Synonyms: PRG-1; KIAA0455; LPPR4; PHP1; PRG1; LPR4
Tractability: Antibody: its Gene Ontology location is reachable by antibodies, with high confidence; UniProt predicts a signal peptide or a membrane-spanning region. PROTAC: its protein half-life has been measured.
Gene: Protein-coding gene on chromosome 1 (99,264,292 to 99,309,590, forward strand). Ensembl gene ENSG00000117600.
Subcellular location: Postsynaptic density membrane
Pathways (Reactome):
Signal Transduction: Lysosphingolipid and LPA receptors
Gene Ontology:
Molecular function: lysophosphatidic acid phosphatase activity; phosphatidate phosphatase activity
Biological process: phospholipid dephosphorylation; axonogenesis; G protein-coupled receptor signaling pathway; lipid import into cell; phospholipid metabolic process; regulation of synaptic transmission, glutamatergic; signal transduction; modulation of chemical synaptic transmission; regulation of postsynapse organization
Cellular component: postsynaptic density membrane; plasma membrane; glutamatergic synapse; Schaffer collateral - CA1 synapse
Genetic constraint (gnomAD): Loss-of-function variants: 21 observed, 52.26 expected, observed/expected ratio (o/e) 0.4, 90% interval 0.28 to 0.58. The upper end of that interval is the gene's LOEUF score, 0.58, which puts it in group 2 of 6, group 1 being the genes least tolerant of losing a copy. Missense variants: 648 observed, 915.91 expected, observed/expected ratio (o/e) 0.71, 90% interval 0.66 to 0.75. Synonymous variants: 324 observed, 340.48 expected, observed/expected ratio (o/e) 0.95, 90% interval 0.87 to 1.04.
Homologues: Orthologues: chimpanzee PLPPR4 (99% identical), macaque PLPPR4 (99% identical), pig PLPPR4 (98% identical), rabbit PLPPR4 (98% identical), mouse Plppr4 (97% identical), guinea pig PLPPR4 (97% identical), rat Plppr4 (97% identical), dog PLPPR4 (96% identical), tropical clawed frog plppr4 (85% identical), zebrafish plppr4a (71% identical), zebrafish plppr4b (63% identical), Drosophila melanogaster CG11437 (11% identical), and 8 more. Paralogues in human: PLPPR3 (48% identical), PLPPR1 (17% identical), PLPPR2 (17% identical), PLPPR5 (15% identical), PLPP1 (12% identical), PLPP3 (11% identical), PLPP2 (11% identical), PLPP5 (9% identical), PLPP4 (9% identical).
Diseases named in the same sentence as PLPPR4 in open-access papers:
PLPPR4 is named in the same sentence as 29 diseases in open-access papers, as found by Europe PMC text mining. Sharing a sentence is not in itself a finding about the gene and the disease. The quoted sentences say what the papers report.
epilepsy (2 papers, 2022 to 2023). A brain disorder characterized by episodes of abnormally increased neuronal discharge resulting in transient episodes of sensory or motor neurological dysfunction, or psychic dysfunction. "PLPPR5, which is positioned on the same chromosome region within 300 kb distance from the PLPPR4 gene in humans and rodents, has also been associated with epilepsy, albeit in a drug-induced animal model." (PMID 36187351, 2022). "Many studies suggest an involvement of PLPPR4 in neurological diseases such as epilepsy, neurotrauma and memory impairment." (PMID 37550884, 2023). "Although the experimental approach differs markedly from the PLPPR4 studies described in the previous paragraph, PLPPR5 KO mice were found to be more prone to epilepsy with a lower seizure latency compared to WT mice." (PMID 36187351, 2022).
gastric cancer (2 papers, 2022 to 2024). A primary or metastatic malignant neoplasm involving the stomach. "PLPPR4 mRNA as well as protein levels are upregulated in some gastric cancer cell lines and its upregulation in gastric cancer is associated with metastasis and poor prognosis." (PMID 36187351, 2022). "PLPPR4 knockdown leads to decreased migration, invasion, wound healing and adhesion in gastric cancer cell lines, while overexpression has the opposite effect." (PMID 36187351, 2022). "Recently, PLPPR4 was identified as a tumor microenvironment-based prognostic marker for gastric cancer." (PMID 36187351, 2022). "Taken together, these results indicate that PLPPR4 promotes gastric cancer metastasis via Sp1-integrin α signaling." (PMID 36187351, 2022).
genetic disorders (1 paper, 2023). "However, PLPPR4 dysfunction has not been linked to genetic disorders." (PMID 37550884, 2023).
neurodevelopmental disorder (1 paper, 2023). A behavioral and cognitive disorder with onset during the developmental period that involves impaired or aberrant development of intellectual, motor, or social functions. "The mechanisms that the mutations in the PLPPR4 gene cause neurodevelopmental disorders were tested in neurons differentiated from patients' iPSCs." (PMID 37550884, 2023). "Our results suggested that the loss of function of PLPPR4 is associated with neurodevelopmental disorders." (PMID 37550884, 2023). "The neurons carrying the deletion of PLPPR4 displayed the reduced density of dendritic protrusions, shorter neurites and reduced axon length, suggesting the causal role of PLPPR4 in neurodevelopmental disorders." (PMID 37550884, 2023). "The findings shed light on the underlying mechanism of neurodevelopmental disorder caused by PLPPR4 mutations and suggest that PLPPR4 is a potential target for gene therapy in disorders of neuronal development." (PMID 37550884, 2023). "It suggested that PLPPR4 drives a cell‐autonomous signalling pathway, which may regulate dendritic spine morphology, and subsequently impaired cognitive function and potentially other neurodevelopmental disorders, including ID and idiopathic ASD in humans." (PMID 37550884, 2023).
psychiatric disorder (1 paper, 2022). A disorder characterized by behavioral and/or psychological abnormalities, often accompanied by physical symptoms. "Regardless of whether other PLPPRs are involved in LPA uptake, PLPPR4 deficiency emerges as a novel correlate to endophenotypes for psychiatric disorders, schizophrenia and resilience to stress." (PMID 36187351, 2022). "On the other hand, behavioral analysis of PLPPR4 heterozygous mice, which are viable and seizure-free, suggest stress-related behavioral changes and altered resilience against psychiatric disorders." (PMID 36187351, 2022). "Furthermore, the PLPPR4 R346T variant detected as a single nucleotide polymorphism in humans, and associated with an endophenotype for psychiatric disorders, is a loss of function mutant for the LPA transporting activity of PLPPR4." (PMID 36187351, 2022).
PLPPR4 also shares sentences with these, for which no sentence is quoted: periodontal disease (2 papers); periodontitis (2); schizophrenia (2); Arrhythmia (1); autism spectrum disorder (1); bone cancer (1); cancer (1); Cirrhosis (1); fatty liver disease (1); hyperlipidemia (1); infection (1); Intellectual disability (1); liver disease (1); liver fibrosis (1); medulloblastoma (1); memory impairment (1); mild cognitive impairment (1); neuroblastoma (1); neurological diseases (1); papillary renal cell carcinoma (1); Parkinson’s (1); primary hyperparathyroidism (1); small cell lung carcinoma (1); tumor (1).